TLR4 (toll like receptor 4)
Diseases named in the same sentence as TLR4 in open-access papers (continued):
Sharing a sentence is not in itself a finding about the gene and the disease.
asthma (continued). "For example, miR-126 expression is up-regulated by TLR4, thereby linking innate immune activation to inflammatory responses through up-regulated miRNAs in asthma, while miR-21 negatively regulates TLR4 after lipopolysaccharide (LPS) stimulation." (PMID 23282474, 2011). "The majority of investigators examining the impact of genetics on responses to environmental microbial exposures in childhood asthma have focused on polymorphisms in CD14, TLR4, and TLR2." (PMID 22151743, 2011). "It has been shown, for example, that inhalation of aerosolized LPS exacerbates allergic airway inflammation in the mouse experimental asthma model through TLR4-mediated mast cell activation and promotion of TH2 responses." (PMID 18687131, 2008). "The elevated expression of TLR4 and TLR1/TLR2 induced by type-2 cytokines is assumed to modulate the impact of bacterial infections on Th2 associated pulmonary diseases like asthma." (PMID 16316467, 2005). "Therefore, in-depth studies of its expression in different cell types, as well as its activation, are necessary to understand the role of TLR4 in asthma." (PMID 40650018, 2025). "Additionally, resveratrol inhibits the HMGB1/TLR4/NFκB pathway, reducing airway inflammation and remodeling, which is crucial for managing asthma-induced airway changes." (PMID 40598285, 2025). "Therefore, the TLR-4/NF-κB axis plays an essential role in modulating immune responses and is considered a major contributor to airway inflammation in asthma." (PMID 40422811, 2025). "TLR4 and its downstream intracellular signaling (mainly involving MAPKs/NF-κB) have been reported to play a certain effect in mediating the occurrence and development of asthma." (PMID 38245791, 2024). "A better understanding of the implication of Toll-like receptor 4 in dendritic cells could contribute to the management of pulmonary diseases including pneumonia, pulmonary tuberculosis, asthma, acute lung injury, and lung cancer." (PMID 39238498, 2024). "Also, another study showed that baicalin mediates the TLR4/NF-κB pathway and upregulates microRNA-103, regulating asthma development in children." (PMID 39263346, 2024). "However, there is little basic research on the role of MD2, an essential helper protein of TLR4, in asthma." (PMID 38245791, 2024). "TLR4, expressed in myeloid cells and airway epithelial cells, may be the main pattern recognition receptor for asthma allergens." (PMID 38245791, 2024). "Similarly, studies have demonstrated that inhibition of TLR4/MyD88/NF-κB signaling can attenuate asthma and protect airways against allergic responses and inflammation." (PMID 39364406, 2024). "Regarding asthma, TLR2, TLR4, TLR7, TLR8, and TLR9 polymorphisms have been elucidated by their implication in allergic and asthma pathways and are also related to allergic and asthma exacerbations." (PMID 37920579, 2023). "Moreover, sputum analysis shows increased toll-like receptors (TLRs), such as TLR2 and TLR4, and several pro-inflammatory cytokines driving T2-low asthma pathobiology." (PMID 37189844, 2023). "Accordingly, both HMGB1/NF‐κB and HMGB1/TLR4 signals may be involved in the occurrence and development of asthma." (PMID 38156383, 2023). "On the one hand, TLR2 and TLR4 are involved in the progression of asthma and T2DM." (PMID 36836906, 2023). "In conclusion, the present research has shown a potential benefit of DEX that modifies both airway inflammation and airway remodeling in a chronic asthma model through the inhibition of the TLR4/NF-κB activity, which provides a novel therapeutic strategy for asthma." (PMID 36846195, 2023). "Additionally, based on the previously published literatures on asthma and inflammation, we screened out down-regulated genes, such as Smg7, Sumo2, and Stat5a, and up-regulated genes, such as Myl9, Fos and Tlr4." (PMID 36726128, 2023).
asthma (continued). "Remarkably, these effects of AG on the BEAS-2B-cell were imitated by the TLR4 inhibitor, which indicated that targeting the TLR4-PKCβ2-NADPH axis might be the pivotal mechanism of AG in ameliorating oxidative stress during asthma." (PMID 37920216, 2023). "Therefore, future studies investigating S100A8/A9 and TLR4 neutralization will be required to determine its potential role in experimental severe asthma." (PMID 36776857, 2023). "Studies have noticed that baicalin could ease asthma symptoms and prolong the incubation period of asthma by affecting the high mobility group box-1/Toll-like receptor 4 signaling pathway." (PMID 36814956, 2023). "Moreover, inhibition of PI3K/Akt/mTOR and TLR4/MyD88/NF-κB signaling with targeted molecules can attenuate pathological mechanisms of asthma and play an important role in protecting airways against allergic response and inflammation pathology." (PMID 35444643, 2022). "Highly purified neutrophils isolated from peripheral blood of asthma patients and healthy donors produced ROS in response to two agonists (LPS and fMLP) that activate specific receptors (TLR4 and FPR, respectively) expressed on the cytoplasmic membrane of these cells." (PMID 34342773, 2022). "We explored whether the administration of Lactobacillus fermentum CECT5716 could reduce the TLR2/TLR4 expression, inhibit the production of inflammatory factors by inflammatory cells, decrease intestinal leakage and pneumonia, and treat asthma." (PMID 35911120, 2022). "Similarly, Alt a 1 probably promotes the development or exacerbation of asthma, possibly due to its ability to interact with TLR4 on alveolar macrophages in the airways." (PMID 35844541, 2022). "Moreover, both agonist and antagonist of TLR4 are used to modify AR or asthma based on activation of TLR4 acting as an adjuvant in allergic vaccines to induce tolerance." (PMID 36434595, 2022). "Furthermore, the inhibition of TLR4/MyD88 signaling by the PEP-NASP peptide in our HDM-induced asthma model significantly decreased mucin hyperexpression and airway inflammation." (PMID 36012669, 2022). "The TLR2/TLR4 expression may affect the secretion of inflammatory factors by the inflammatory cells, which regulate the target of asthma progression." (PMID 35911120, 2022). "In the progression of asthma, lung IMs may be tightly related to TLR4/MyD88 pathway to produce IL-10 for anti-inflammation and to regulate Th2- and Th17-mediated inflammation." (PMID 36582191, 2022). "The PPI and KEGG analyses indicated that TLR4 might be one of the targets of Danlong Dingchuan Decoction in treating asthma, as further confirmed by the molecular docking results." (PMID 35186104, 2022). "The results of the current study are concordant with recent in vivo studies in which propofol suppressed inflammatory cytokine production via inhibition of TLR4-dependent pathways in various disease models, including lung, liver, and gastric injuries, and asthma." (PMID 36117859, 2022). "In the cellular and mouse model of asthma, lipopolysaccharide (LPS) could combine with toll-like receptor 4 (TLR4) to activate myeloid differentiation primary response 88 (MyD88), and the nuclear transposition of NF-κB happened then." (PMID 36582191, 2022). "Thus, HDM-exposed mice (both wild-type mice that inhaled TLR4 inhibitor and TLR4–/– mice) were shown to display reduced asthma features." (PMID 34248677, 2021). "In addition, the TLR4-NF-kappaB pathway has been demonstrated to accelerate the pathological process of asthma by inducing autophagy and apoptosis of tracheal epithelial cells." (PMID 33645621, 2021). "The role of TLR4 in promoting asthma was further explored by inhibiting or silencing the gene." (PMID 34248677, 2021). "However, TLR4 as an adjuvant of AIT for AR or asthma is unclear, but LPS has been used to stimulate TLR4 in many animal studies." (PMID 35387059, 2021). "Several possible mechanisms might account for Toll-like receptor 4 (TLR-4) mediated effects in atopy and asthma." (PMID 33324411, 2020).
asthma (continued). "The authors used intranasal injections for 21 days to address whether the induction of asthma by Der p 2 is TLR4- and MD-2 dependent." (PMID 33424827, 2020). "However, little is known about the role of TLR4 gene variations in the NP bacterial colonization or its consequent impact on the development of childhood asthma." (PMID 32650475, 2020). "In addition, knockout mice in TLR4 and MyD88 are attenuated in Th2 cytokines, IL-17, neutrophilia, and bronchial hyperreactivity compared to WT." (PMID 33424827, 2020). "TLR4 plays a key role in the allergic inflammation and severity of asthma.We hypothesize that the prevalence of the fibronectin receptors, notably TLR4, on the DC surface impairs the effects of stimulation by OfHz." (PMID 31750318, 2019). "The filarial nematode-derived immunomodulator, ES-62 protects against development of asthma in both acute and chronic mouse models at least in part by suppressing FεcRI- and LPS/TLR4-mediated activation of mast cells and downregulation of type-2 inflammatory responses." (PMID 29540770, 2018). "Our objective was to examine associations between single nucleotide polymorphisms (SNPs) and combinations of SNPs in the toll-like receptor 4 (TLR4) pathway, residential distance to roadway as a proxy for traffic-related air pollution exposure, and asthma diagnosis and exacerbations." (PMID 30140039, 2018). "Therefore, it was possible that paeonol attenuated OVA-induced asthma by restraining TLR4/NF-κB/MIP-1β pathway." (PMID 30186353, 2018). "The results showed that, compared with WT mice, tlr2−/−, and tlr4−/− mice exhibited increased infiltration of leukocytes, especially asthma-related eosinophils, in alveoli, and IgE level in serum was increased significantly in tlr2−/− and tlr9−/− mice after allergic asthma establishment." (PMID 30510553, 2018). "Intracellular ROS generation in airway epithelial cells by HDM allergen or viral RNA sensor activation thus share, through confluent signaling, pleiotropic operational elements (thrombin, ADAM 10, EGFR, TLR4) fundamental to the progression of allergic sensitization and asthma exacerbations." (PMID 29542272, 2018). "To test a proof-of-principle of this hypothesis with asthma, we examined associations between combinations of specific SNPs along the TLR4 inflammatory pathway, air pollution exposure, and asthma-related health outcomes." (PMID 30140039, 2018). "Accordingly, it was found that Asp299Gly polymorphism in the extracellular domain of the TLR4 receptor that causes an important reduction of TLR4 function resulted in increased risk to infections or to develop shock but not asthma." (PMID 29867994, 2018). "These include antagonists of TLR4, such as TLR4 targeted monoclonal antibody NI-0101, by Novimmune, which has several potential applications including asthma and rheumatoid arthritis and is the first antibody for TLR4 to pass Phase I clinical trials for safety and tolerability." (PMID 28553556, 2017). "We evaluated whether post-bronchiolitis asthma was associated with polymorphisms in the TLR3 rs3775291, TLR4 rs4986790, TLR7 rs179008, TLR8 rs2407992, TLR9 rs187084, and TLR10 rs4129009 genes." (PMID 28592890, 2017). "Thus, the aim of this study was to investigate the role of TLR4 in asthma-like features such as inflammatory infiltrate, airway hyperreactivity, and mucus exacerbation in mice exposed to S1P." (PMID 29093714, 2017). "This outcome may result from a link between innate immunity and IgE-mediated, adaptive immune responses in asthma, and point to TLR4 as a potential therapeutic target." (PMID 27084682, 2016). "Since KSpn, targets both TLR2 and TLR4, it may have increased potential for effective suppression of asthma, and S. pneumonia components or vaccines, may have applicability as human therapies." (PMID 27309732, 2016).
asthma (continued). "In addition to TLR4, variants of the TLR2 gene were reported to have some association with childhood asthma in Caucasians, and TLR2 polymorphism affects the asthma risk and lung function." (PMID 27274620, 2016). "Some have shown that TLR2 and TLR4 agonists may be beneficial in asthma, whereas others show that some TLR4 agonists such as lipopolysaccharide (LPS) exacerbate disease." (PMID 27309732, 2016). "For TLR2 and TLR4 expression at 9 h is also significantly higher in asthma than in ABPA." (PMID 27708669, 2016). "Since TLR2 and TLR4 are important in innate immunity and asthma, and recognize components of S. pneumoniae, we hypothesized that these receptors play an important role in the development of AAD and S. pneumoniae-mediated suppression of AAD." (PMID 27309732, 2016). "In addition to TLR4, polymorphisms present in the TLR2 gene are also associated with the risk of asthma development and overall lung function." (PMID 26617525, 2015). "Heterozygous TLR4 genotypes (TLR4 A896G and TLR4 C1196T polymorphisms) were more frequent in the moderate asthma group, but this association was not statistically significant." (PMID 24524443, 2014). "Numerous studies have implicated TLR2, TLR4 and TLR9 in the pathogenesis of asthma or atopy." (PMID 24524443, 2014). "LPS reduced asthma by transmembrane Toll-like receptor 4 (TLR4)-mediated mechanisms." (PMID 24671176, 2014). "Finally, inhalation of a TLR4 antagonist to target exposed epithelial cells suppressed the features of asthma, including bronchial hyperreactivity." (PMID 23724247, 2013). "Although some TLRs showed associations with asthma in childhood, the most investigated TLR4 did not." (PMID 23496969, 2013). "Interestingly, polymorphisms of the genes encoding TLR4 and CD14 were found to influence the severity of asthma and its relation with endotoxin exposure." (PMID 23724247, 2013). "The polymorphisms rs4696480 and rs1898830 in TLR2 and the polymorphisms rs2770150, rs10759931, rs6478317, rs10759932, and rs1927911 in TLR4 increased the effect of fine particulate matter exposure on the prevalence of doctor-diagnosed asthma from birth up to eight years of age." (PMID 23496969, 2013). "Increased TLR signaling was commonly associated with several pulmonary diseases and there is growing evidence that asthma and atopy are positively associated with polymorphisms in genes coding for TLR2, TLR4, TLR1, and TLR6 as well as TLR-related MyD88-dependent pathway molecules." (PMID 23724247, 2013). "Interestingly, inhalation of a TLR4 antagonist to target ECs suppressed the salient features of asthma, including bronchial hyperreactivity." (PMID 21943186, 2011). "Finally, in a multi-centre asthma study, TLR4 and TLR9 were both associated with wheezing and TLR4 was also associated with allergen specific IgE secretion." (PMID 21108806, 2010). "Interestingly, previous studies had shown the anti-inflammatory function of MUC1 in asthma, by reducing the NLRP3 inflammasome-mediated pyroptosis through the inhibition of the TLR4/MyD88/NF-κB pathway, thereby suppressing neutrophilic airway inflammation in patients with asthma." (PMID 41295249, 2025). "Therefore, whether there is increased binding of MD2 and TLR4 in our asthma model was determined through co-immunoprecipitation assay." (PMID 38245791, 2024). "In addition, the main signaling pathway of HMGB1 involved in asthma is HMGB1/TLR4/NF‐κB and HMGB1/RAGE, while whether the JAK/STAT signaling pathway is involved in HMGB1 still unclear at present." (PMID 38156383, 2023). "Therefore, the TLR4/NF-κB signaling pathway may act as a potent target for developing novel treatments against asthma." (PMID 36846195, 2023). "However, whether MUC1 regulates NLRP3 inflammasome-mediated pyroptosis through the TLR4/MyD88/NF-κB pathway in asthma remains unknown." (PMID 37880668, 2023). "Therefore, TLR4/NF-κB- and Egr-1- mediated inflammatory response and oxidative stress might be important therapeutic targets for asthma." (PMID 37451839, 2023).
asthma (continued). "GLA could also downregulate the expression of TLR4 in the lung of asthma mice." (PMID 35859797, 2022). "Importantly, the TLR4/MyD88/NF-κB axis is reported to partake in asthma’s pathogenesis." (PMID 35156897, 2022). "The animal experiments verified that Danlong Dingchuan Decoction could effectively reduce IL-4, IL-6, IL-8, and IL-1β expression in the lung tissue of asthmatic mice, decrease TLR4 mRNA expression, and inhibit Th2 cytokine-mediated inflammatory response to treat asthma." (PMID 35186104, 2022). "NETs could thus enhance local inflammation by activating TLR4 expressed by the airway epithelium and then promote chronic inflammation, tissue lesions and by this way worsen respiratory symptoms as observed in severe quine asthma." (PMID 35911691, 2022). "Besides, high mobility group box 1 (HMGB1) secreted by some injury cells or immune cells in asthma could promote the activation of TLR4, inhibited by heat shock factor 1 (HSF1), when bound with HMGB1 promotor." (PMID 36582191, 2022). "This may also suggest that the genetic variation of TLR4 could not directly be linked to the development of asthma." (PMID 32650475, 2020). "In this present study, we could not find any direct associations between studied TLR4 polymorphism and an asthma risk." (PMID 32650475, 2020). "In particular, Toll-like receptor 4 (TLR4) is known as a critical driver of the innate immune response to bacterial infections, and its dysregulation can contribute to a variety of diseases, such as: asthma, cardiovascular disease, metabolic syndrome, autoimmune disorders, and even schizophrenia." (PMID 33291425, 2020). "Also, experimental asthma could be established when OVA allergen is administrated together with flagellin as an adjuvant even in Tlr4−/− C57BL/6 and BALB/c mice." (PMID 29867994, 2018). "The present study was carried out to complement this exploratory study series by evaluating whether the TLR3 rs3775291, TLR4 rs4986790, TLR7 rs179008, TLR8 rs2407992, TLR9 rs187084, and TLR10 rs4129009 polymorphisms are associated with post-bronchiolitis asthma." (PMID 28592890, 2017). "Indeed, in HDM-mediated asthma models, TLR4 expression by airway epithelial cells has been shown to contribute in a MyD88-dependent but TRIF-independent fashion to the development of an IL1-, alarmin-, and GM-CSF-mediated DC activation to allow the development of a pathogenic Th2 response." (PMID 29201030, 2017). "However, we found that TLR4 was significantly decreased in alveolar lavage fluid in severe asthma, which may be due to the fact that in the inflammatory milieu of severe asthma, some inhibitory factors may be produced, which can downregulate the expression of TLR4." (PMID 40160461, 2025). "Gene and protein expression of the four potential asthma triggers, AKT1, MAPK13, STAT1, and TLR4, was analyzed in PBMC samples obtained from AA, NA, and HC." (PMID 40650018, 2025). "Here, we have analyzed theoretical signaling pathways related to four asthma trigger proteins, AKT1, MAPK13, STAT1, and TLR4, defined by previous systems biology study as proteins able to modify the activation of many effector proteins of respiratory diseases." (PMID 40650018, 2025). "The interaction between TLR4 and HMGB1 activates the NF-κB pathway, leading to the synthesis of inflammatory mediators and exacerbation of asthma symptoms." (PMID 40672946, 2025). "In the murine asthma model study, HMGB1 has been confirmed to directly and indirectly induce Th17 immune response by TLR4‐NF‐κB signal pathway." (PMID 38414294, 2024). "The TLR4 pathway can be activated and lead to disease exacerbation in the OVA-triggered asthma model." (PMID 38245791, 2024). "In asthma, HMGB1 expression induces HSP expression through the TLR4 / MYD88 / NF-kB pathway, which eventually produces IL-4 and IL-13." (PMID 37422662, 2023). "HMGB1/TLR4/NF‐κB, HMGB1/RAGE, JAK/STAT, and HMGB1/TGF‐β play important roles in the occurrence and development of asthma." (PMID 38156383, 2023).